HMGA2 (high mobility group AT-hook 2)
Diseases named in the same sentence as HMGA2 in open-access papers (continued):
Sharing a sentence is not in itself a finding about the gene and the disease.
breast cancer (continued). "Research has shown overexpression of HMGA2 in a variety of cancers [e.g., colorectal cancer (CRC), liver cancer, breast cancer (BC), and uterine leiomyomas], suggesting an essential role in tumor development and invasion." (PMID 38361784, 2024). "Meanwhile, cellular uptake, in vitro HMGA2 gene silencing efficiency, selective cytotoxicity, and cell apoptosis of G4/MTX-siRNA were examined on MCF-7 and MDA-MB-231 (human breast cancer) cells." (PMID 34356120, 2021). "Not surprisingly, OSM has also been shown to induce EMP by regulating the Lin28/Let7/HMGA2 and miR200/Zeb1 circuits via STAT3 in breast cancer, leading to the initiation and maintenance of an EMP program both in vitro and in vivo." (PMID 34361105, 2021). "This demonstrated that HMGA2 promoter methylation was significantly lower in the TNBC and HER2+ breast cancer tissues compared to luminal breast cancer tissues (p = 9.43 × 10−4) and normal tissues (p = 4.78 × 10−11)." (PMID 34680349, 2021). "This is consistent with prior research findings that HMGA2 induces sphere formation and promotes the expression of cancer stem cell markers, including CD44, ALDH1, CD133 in gastric and breast cancer." (PMID 34680349, 2021). "Ectopic expression of miR-33b, which affects the levels of HMGA2, SALL4 and Twist1, can decrease the stem cell-like properties of breast cancer cells." (PMID 31979076, 2020). "After breast cancer MCF‐7 and BT‐474 cells were treated with an increased dose of metformin, the mRNA and protein level of HMGA2 was evaluated through western blotting and RT‐PCR assays." (PMID 32031335, 2020). "Thus, we found that HMGA2 could be reduced by metformin in breast cancer." (PMID 32031335, 2020). "In breast cancer, both HMGA1 and HMGA2 play a role in maintaining stem cell properties to the tumor cells." (PMID 31963852, 2020). "PARylation of HMGA2 following alkylating DNA damage provided further evidence for a functional interaction between PARP1 and HMGA2 in fibrosarcoma and breast cancer cells." (PMID 30289618, 2019). "HMGA2, SALL4, and Twist1 are overexpressed in breast cancer, facilitating the self-renewal of CSCs, and enlarging the population of CSCs, leading to the tumor acquiring a higher invasive and metastatic ability." (PMID 31861404, 2019). "Altered expression of HMGA2, POLE2 and TRIB3 was predictive of survival among members of the Metabric breast cancer cohort." (PMID 30763339, 2019). "Of the 23 co-expressed mRNAs identified through RNA-seq, we demonstrated that overexpression of HMGA2, POLE2 and TRIB3 reduced metastasis-free survival in Metabric Breast Cancer cohort from TCGA, as observed by Kaplan Meier analysis." (PMID 30763339, 2019). "Concomitantly, in breast cancer models, RKIP induction was able to suppress tumor cell proliferation and invasion by upregulating miR-185, an upstream negative regulator of HMGA2." (PMID 30149591, 2018). "Remarkably, we found that breast cancer cells treated with NS1643 presented a strong increase of the HMGA2 nuclear foci, suggesting that HMGA2 can contribute to NS1643-dependent senescence and DNA damage." (PMID 29423049, 2018). "Overexpression of PAR1, a GPCR, promotes invasion and metastasis in breast cancer cells and inhibition of PAR1 signaling suppresses HMGA2-driven invasion in breast cancer cells." (PMID 28288630, 2017). "HMGA2 dysregulation is correlated with poor survival for patients with CRC and promotes breast cancer metastasis by increasing LOX expression." (PMID 26968810, 2016). "Because HMGA2 regulates LOX expression, we continued to detect the downstream effectors of LOX in breast cancers." (PMID 25919570, 2015). "We also analyzed cDNA microarray data in Oncomine34 to further confirm the role of HMGA2, SALL4 and Twist1 in breast cancer pathogenesis." (PMID 25919570, 2015).
breast cancer (continued). "The ectopic expression of miR-33b downregulated the expression of ADAM9, HMGA2, LDHA, SALL4, SNAI2 and Twist1 by more than 30% but had minimal effects on HIF-1α, RAC1, Yes1 and ZEB1 in these two breast cancer cell lines." (PMID 25919570, 2015). "Our data demonstrated that miR-33b dramatically downregulated the expression of HMGA2, SALL4 and Twist1 in breast cancer cells to suppress cell self-renewal." (PMID 25919570, 2015). "We therefore compared the expression patterns of HMGA2 and CDH1 in human breast cancer cells using the GOBO tool." (PMID 25492890, 2015). "MA-11 cells were originally isolated from a malignant bone marrow metastasis of a breast cancer patient and express high levels of both WNT10B and HMGA2." (PMID 23307470, 2013). "In summary, we have presented evidence supporting that HMGA2 expression is a clinical marker that has the capacity to predict survival outcome in TNBC and basal-like breast cancer patients." (PMID 23307470, 2013). "Although WP’s involvement in the subtype specific BC has been reported recently, in the context of HMGA2 induction and proliferation in metastatic triple-negative breast cancer, its role in the context of BC heterogeneity, subtype specific genomic events, and outcome remains undecided." (PMID 24143235, 2013). "Our findings emphasize the potential of the HMGA2 associated HOTAIR axis as a prognostic biomarker and therapeutic target, especially in ER negative, postmenopausal onset, and relapsed breast cancer." (PMID 40686703, 2025). "Also there are evidences which shows the regulatory role of let-7 family on breast cancer metastasis and stemness mostly by targeting oncogenes such as RAS, HMGA2." (PMID 39716374, 2024). "While an analysis of 1,097 breast cancer samples in the TCGA data set did not identify HMGA2 as a significant prognostic marker in breast cancer overall, its expression is predictive of relapse-free survival and metastasis in patients with TNBC." (PMID 36568239, 2022). "The proinflammatory signals in M1 macrophages induce stemness properties in nonstem breast cancer cells through STAT3/NF-κB signaling via activation of lin-28B/let-7/HMGA2." (PMID 33668453, 2021). "Furthermore, HMGA2 protein level was remarkably enhanced in MDA-MB-231 and MDA-MB-453 cells compared with MCF-10A cells, and it was further up-regulated in resistant breast cancer cells." (PMID 34281530, 2021). "Barh demonstrated that in silico analysis, apart from repressing HMGA2, RAS, and MYC, let-7 may also target CYP19A1, ESR1, and ESR2, thereby potentially blocking estrogen signaling in ER-positive breast cancers." (PMID 34442460, 2021). "Furthermore, several studies have demonstrated that HMGA2 participates in 5-FU resistance in some malignancies, such as CRC, breast cancer, and liver cancer." (PMID 34844630, 2021). "HER2-positive breast cancers exhibited reduced HMGA2 levels, while no change was observed for the luminal subgroup." (PMID 34680349, 2021). "Chromatin immunoprecipitation (ChIP) assay was performed to show the binding of Sp1 to HMGA2 promoter in breast cancer cells with or without metformin treatment." (PMID 32031335, 2020). "Our work found that PAR1 induced a basal-like phenotype in human breast cancer cell lines through the non-histone chromatin-binding protein and a high-mobility-group non-histone chromosomal protein called HMGA2." (PMID 30065181, 2018). "A codelivery therapy that inhibits HMGA2 by siRNA and acts on DNA by doxorubicin showed efficacy in CRC and the same dual treatment inhibits cell growth, vimentin (stemness marker), and MMP9 (invasion marker) in breast cancer cells." (PMID 29853899, 2018). "Moreover, TET1 promoter was methylated in high-mobility group AT-hook 2 (HMGA2; chromatin remodeling factor)-depleted breast cancer cells." (PMID 25557833, 2015).
breast cancer (continued). "This hypothesis is supported by recent data which demonstrate that let-7, due to its ability to decrease the levels of HMGA2 resulting in the down regulation of CXCR4, inhibits the formation of breast cancer bone metastases." (PMID 25909161, 2015). "Because both Twist1 and HMGA2 can regulate the proteins responsible for ECM degradation, we speculated that miR-33b may regulate migration and invasion in breast cancer cells via matrix remodeling." (PMID 25919570, 2015). "In addition, and relevant to this study, the MDA-MB-231 cell line also expressed high levels of endogenous HMGA2, compared to many epithelial breast cancer cell lines of the luminal type, such as MCF7, which expressed E-cadherin but low amounts of HMGA2." (PMID 25492890, 2015). "In addition, miRNA can act pleiotropically; therefore, HMGA2, SALL4 and Twist1 are the ideal targets of miR-33b in modulating the stemness of breast cancer cells." (PMID 25919570, 2015). "For example, miR-196a has been studied for its oncogenic roles in glioblastoma, pancreatic adenocarcinoma, breast cancer, oesophageal adenocarcinoma, and colorectal cancer, and shown to target HOX family genes (HOXA7, HoxB7, HOXC8, HOXB8, HOXD8), ERG, HMGA2, ANXA1, S100A9, SPRR2C, KRTS." (PMID 24621885, 2014). "In our in silico analysis, we recently showed that, apart from repressing MYC, ras, and HMGA2, let-7 may also target CYP19A1, ESR1, and ESR2, thereby potentially blocking estrogen signalling in er-positive breast cancers." (PMID 20179807, 2010). "Furthermore, HMGA2 expression has been shown to be associated with enhanced selective chemosensitivity towards the topoisomerase (topo) II inhibitor, doxorubicin, in breast cancer HS578T and salivary Pa-4/HMGA2 cells." (PMID 17222355, 2007). "Our findings are not restricted to thyroid cancer since HMGA2 has several times been identified as correlating with tumor aggressiveness in other cancers such as breast cancer, tongue squamous cell carcinoma and ovarian cancer, highlighting the common oncogenic role of HMGA2 in tumor progression." (PMID 40004107, 2025). "In breast cancer (BC), HOTAIR upregulates HMGA2 expression by competitively binding to miR-20a-5p, resulting in cell growth, metastasis, and apoptosis." (PMID 35813070, 2022). "In addition, NEAT1 could increase the expression of high mobility group AT-hook 2 (HMGA2) by sponging miR-211, thereby enhancing the invasiveness of breast cancer cells." (PMID 34527584, 2021). "Further studies in breast cancer models revealed that RKIP may also prevent tumor cell invasion and metastasis indirectly, by negative regulation of critical prometastatic factors downstream of let-7, including high mobility group AT-hook 2 (HMGA2) and BACH1." (PMID 30149591, 2018). "Treatment with 5-aza was sufficient to demonstrate significant E-cadherin protein re-expression in MDA-MB-231 cells, which implies that genetic manipulation of HMGA2 alone in breast cancer cells is not sufficient to re-establish a demethylated state on chromatin." (PMID 25492890, 2015). "Interestingly, despite the knockdown of HMGA2 in MDA-MB-231 breast cancer cells, E-cadherin protein was not re-expressed." (PMID 25492890, 2015). "In breast cancers, inhibition of MAPK suppresses invasion and metastasis in part by increasing let-7 expression, which leads to suppression of the let-7 targets High-mobility group AT-hook 2 (HMGA2) and BTB-and CNC homology 1 leucine zipper transcription factor (BACH1)." (PMID 25546138, 2014). "HMGA2 is expressed during embryogenesis and is generally not or rarely expressed in adult tissues, which makes it an interesting therapeutic target since it is re-expressed in various types of human cancer, including prostate cancer, breast cancer, oesophageal cancer and thyroid cancer." (PMID 37445942, 2023).
breast cancer (continued). "The anti-tumorigenic effect of let-7 by targeting both HMGA2 and BACH1 is especially effective in abrogating bone metastasis in a breast cancer model where the two proteins share some but not all of the same target genes." (PMID 25546138, 2014). "Moreover, we found that miR-33b does not alter the 3′UTR activity of the well-established EMT transcription factor SNAI2, suggesting that miR-33b regulates HMGA2, SALL4 and Twist1 in breast cancer cells without impacting EMT." (PMID 25919570, 2015). "Furthermore, nuclear HMGA2 expression is restricted to TNBC as it was not detectable in ERα+, PR+, HER2+ and triple positive (TP) breast cancer samples." (PMID 23307470, 2013).
colorectal cancer (98 papers, 2011 to 2026). A primary or metastatic malignant neoplasm that affects the colon or rectum. "Low HMGA2 expression was linked to microsatellite instability in colorectal cancer (p = 0.0002) and HPV infection in squamous cell carcinomas (p < 0.0001)." (PMID 40518465, 2025). "HMGA2 is involved in neoplastic transformation and its expression is associated with poor survival in colorectal cancer." (PMID 31692974, 2019). "In particular, overexpression of HMGA2 has been demonstrated to associate with neoplastic transformation and tumor progression in Colorectal Cancer (CRC)." (PMID 26893968, 2016). "Recent studies have demonstrated that thyroid hormones can promote the nuclear accumulation of HMGA2 and β-catenin in colorectal cancer cells, with varying K-RAS mutation states, in a concentration-dependent manner, ultimately facilitating cancer proliferation." (PMID 40747299, 2025). "Conversely, hsa‐miR‐9‐5p increases 5‐FU sensitivity in colorectal cancer by downregulating High Mobility Group AT‐Hook 2 (HMGA2)." (PMID 40444136, 2025). "The role of HMGA2 critically depends on specific cellular environments fits well with the strong inverse correlation with MSI in colorectal cancer (CRC) and HPV infection in squamous cell carcinomas." (PMID 40518465, 2025). "In this study, we showed that HMGA2 is overexpressed in colorectal cancer tissue, and knockdown of HMGA2 significantly inhibited colorectal cancer cell growth and migratory capability." (PMID 38845972, 2024). "YTHDC1 promoted the cytoplasmic output of methylated circNSUN2, regulates the stability of HMGA2, and promotes liver metastasis of colorectal cancer." (PMID 38978074, 2024). "Previous studies have suggested that HMGA2 overexpression can play critical roles in chemoresistance in various cancers, such as promoting 5-FU drug resistance in gastric and colorectal cancers." (PMID 38845972, 2024). "In summary, our results showed that HMGA2 is overexpressed in colorectal cancer and HMGA2 regulates colorectal cancer cell growth." (PMID 38845972, 2024). "Our results highlight the importance of HMGA2 function and can help determine potential therapeutic targets for colorectal cancer treatment." (PMID 38845972, 2024). "Our results provide a basic molecular mechanism of HMGA2 and shed light on drug application for colorectal cancer therapy." (PMID 38845972, 2024). "For instance, circNSUN2 forms a ternary complex with IGF2BP2 and high mobility group A (HMGA2) mRNA in the cytoplasm which stabilizes mRNA, and then upregulation of HMGA2 induces epithelial-mesenchymal transition and enhances colorectal cancer aggressiveness." (PMID 38724502, 2024). "The mouse that had the intestine-specific Hmga2 overexpression accelerated azoxymethane (AOM)/dextran sodium sulfate (DSS) carcinogen-induced tumor development, suggesting an important role of HMGA2 in colorectal cancer development." (PMID 38845972, 2024). "Amentoflavone exerts antitumor effects by inhibiting colorectal cancer EMT through the miR‐16‐5p/HMGA2/β‐catenin pathway." (PMID 38842135, 2024). "High-mobility gene group A2 (HMGA2) is overexpressed in colorectal cancer, contributing to the aggressiveness of tumor malignance, and promotes drug resistance in many types of cancer." (PMID 38845972, 2024).
colorectal cancer (continued). "The N6-methyladenosine (m6A) modification of circNSUN2 stabilizes HMGA2 mRNA, enhancing colorectal carcinoma metastasis by forming a circNSUN2/IGF2BP2/HMGA2 RNA-protein complex." (PMID 39253079, 2024). "In the cytoplasm, the stability of HMGA2 mRNA was improved when the circNSUN2/IGF2BP2/HMGA2 RNA-protein ternary complex was created by circNSUN2, thus aiding in the advancement of colorectal cancer metastasis." (PMID 37489458, 2023). "In line with our findings, HMGA2 has been reported to be upregulated in oxaliplatin-resistant colorectal cancer, thus further strengthening the findings that HMGA2 functions in the clearance of DNA lesions induced by oxaliplatin." (PMID 38058548, 2023). "Increasing miR-330 expression in human colorectal cancer cells was reported to induce apoptosis and suppresses cell viability and migration through inhibition of HMGA2 and Smad3 expression." (PMID 37077419, 2023). "Our results are consistent with previous studies which also found overexpression of HMGA2 to correlate with worse prognosis in cancers of the breast, lung, pancreas, ovaries, as well as gastric cancer, colorectal cancer, and oral cancer." (PMID 35388973, 2022). "For example, in many cancers such as colorectal cancer and endometrial cancer, HMGA2 and Wnt signaling pathway have a synergistic regulatory effect." (PMID 35903696, 2022). "Another study reveals that circNSUN2 modulates the cytoplasmic exportation of a ternary RNA-protein complex (i.e., circNSUN2/IGF2BP2/HMGA2), while enhancing the stability of HMGA2 mRNA, which in turn promotes colorectal cancer metastases." (PMID 36814375, 2022). "For example, the m6A modification of circNSUN2 increases its export to the cytoplasm and circNSUN2 enhances the stability of HMGA2 mRNA to promote colorectal carcinoma metastasis progression, forming a circNSUN2/IGF2BP2/HMGA2 RNA-protein ternary complex." (PMID 35999496, 2022). "Together, the circNSUN2/IGF2BP2/HMGA2 mRNA complex stabilizes HMGA2 mRNA to promote colorectal cancer metastasis." (PMID 34449657, 2021). "In earlier studies, we demonstrated G2/M arrest in both breast and colorectal cancer in response to HMGA2 knockdown." (PMID 33668453, 2021). "Overexpression of HMGA2 enhances chemoresistance to 5-Fluorouracilfluorouracil (5-FU) via activation of the Wnt pathway in both in vitro and in vivo experiments of colorectal cancer." (PMID 33668453, 2021). "There is experimental evidence that IGF2BP2 can promote the metastasis of colorectal cancer through the formation of circNSUN2/IGF2BP2/HMGA2 protein ternary complex in the cytoplasm." (PMID 33952279, 2021). "CircNSUN2 formed a circNSUN2/IGF2BP2/HMGA2 complex in the cytoplasm, which facilitated the exportation and stabilization of HMGA2 in colorectal cancer." (PMID 34873163, 2021). "Lastly, in colorectal cancer cells, replacement of miR-194 results in this miRNA targeting HMGA2 coexpressed genes through the TGFβ signaling pathway and this decreases cell viability in response to oxaliplatin and irinotecan." (PMID 33668453, 2021). "PCAT6 induced colorectal cancer resistance to 5‐fluorouracil‐based chemotherapy by sponging miR‐204 and activating the HMGA2 pathway." (PMID 34185427, 2021). "By forming the RNA-protein ternary complex of circNSun2/IGF2BP2/HMGA2 in the cytoplasm, circNSun2 enhances the stability of HMGA2 mRNA and promotes colorectal cancer cell infiltration and liver metastasis." (PMID 33552994, 2020). "When removed to the cytoplasm, CircNSUN2 bind to reader IGF2BP2, combine with downstream HMGA2 mRNA to improve the stability of HMGA2 mRNA, and ultimately promote liver metastasis of colorectal cancer tumors." (PMID 33237039, 2020). "HMGA2, a high mobility group AT-hook 2, is already widely believed to be related to the progression of colorectal cancer." (PMID 32522202, 2020).